FAM66D (family with sequence similarity 66 member D)
Gene: Long non-coding RNA gene on chromosome 8 (12,115,767 to 12,202,753, forward strand). Ensembl gene ENSG00000255052.
Diseases named in the same sentence as FAM66D in open-access papers:
FAM66D is named in the same sentence as 7 diseases in open-access papers, as found by Europe PMC text mining. Sharing a sentence is not in itself a finding about the gene and the disease. The quoted sentences say what the papers report.
inflammatory bowel disease (2 papers, 2022 to 2025). A spectrum of small and large bowel inflammatory diseases of unknown etiology. "On the other hand, the FAM66D locus encodes a LINC RNA species whose expression is significantly upregulated in both Crohn’s disease (CD) and ulcerative colitis (UC), the two most common types of inflammatory bowel disease (IBD)." (PMID 36405926, 2022).
colorectal cancer (1 paper, 2025). A primary or metastatic malignant neoplasm that affects the colon or rectum. "Since Fusobacterium has been shown to promote colorectal cancer (CRC), we believe that the CNV of FAM66D in the genome can also be used as a risk assessment indicator for CRC." (PMID 40659563, 2025).
cancer (1 paper, 2025). A tumor composed of atypical neoplastic, often pleomorphic cells that invade other tissues. "Considering the positive correlation between Fusobacterium and cancer, we believe that people with a high CNV of FAM66D may be associated with cancer and intestinal inflammatory disease." (PMID 40659563, 2025). "It has been previously reported that FAM66D is a lncRNA that plays a promoting role in IBD and the development of cancer." (PMID 40659563, 2025).
tumor (1 paper, 2025). "FAM66D was previously considered to be a lncRNA involved in IBD and tumor growth." (PMID 40659563, 2025).
FAM66D also shares sentences with these, for which no sentence is quoted: Crohn disease (1 paper); gastric cancer (1); ulcerative colitis (1).